IL1RAPL1 (interleukin 1 receptor accessory protein like 1)
Description:
May regulate secretion and presynaptic differentiation through inhibition of the activity of N-type voltage-gated calcium channel. May activate the MAP kinase JNK. Plays a role in neurite outgrowth (By similarity). During dendritic spine formation can bidirectionally induce pre- and post-synaptic differentiation of neurons by trans-synaptically binding to PTPRD (By similarity).
Synonyms: IL-1-RAPL-1; IL-1RAPL-1; IL1RAPL-1; TIGIRR-2; OPHN4; IL1R8; IL1RAPL; MRX10; MRX21; MRX34
Tractability: Small molecule: it has a binding pocket of medium quality. Antibody: UniProt places it where antibodies can reach, with high confidence; its Gene Ontology location is reachable by antibodies, with high confidence; UniProt predicts a signal peptide or a membrane-spanning region. PROTAC: its protein half-life has been measured.
Gene: Protein-coding gene on chromosome X (28,587,446 to 29,956,718, forward strand). Ensembl gene ENSG00000169306.
Subcellular location: Cell membrane; Cytoplasm; Cell projection, axon; Cell projection, dendrite
Pathways (Reactome):
Immune System: Interleukin-38 signaling
Neuronal System: Receptor-type tyrosine-protein phosphatases
Gene Ontology:
Molecular function: interleukin-1 binding; protein binding; signaling receptor binding; NAD+ nucleosidase activity, cyclic ADP-ribose generating
Biological process: negative regulation of exocytosis; regulation of postsynapse organization; regulation of presynapse assembly; trans-synaptic signaling by trans-synaptic complex; cell surface receptor signaling pathway; neuron differentiation; positive regulation of dendritic spine morphogenesis; positive regulation of synapse assembly; presynaptic membrane assembly; regulation of neuron projection development; synaptic membrane adhesion; signal transduction
Cellular component: cytoplasm; glutamatergic synapse; plasma membrane; cell surface; dendrite; postsynaptic membrane; axon
Gene-disease validity (ClinGen):
ClinGen rates the evidence that IL1RAPL1 causes each of these diseases.
non-syndromic X-linked intellectual disability (X-linked): Definitive. Nonspecific X-linked intellectual deficiencies (MRX) belong to the family of sex-linked intellectual deficiencies (XLMR).
Homologues: Orthologues: chimpanzee IL1RAPL1 (100% identical), macaque IL1RAPL1 (99% identical), dog IL1RAPL1 (99% identical), rabbit IL1RAPL1 (99% identical), pig IL1RAPL1 (99% identical), guinea pig IL1RAPL1 (99% identical), rat Il1rapl1 (99% identical), mouse Il1rapl1 (99% identical), tropical clawed frog il1rapl1 (91% identical), zebrafish il1rapl1a (69% identical), zebrafish il1rapl1b (53% identical). Paralogues in human: IL1RAPL2 (61% identical), IL1RAP (27% identical), IL18RAP (22% identical), IL1R1 (21% identical), IL18R1 (21% identical), IL1RL2 (20% identical), IL1RL1 (20% identical), IL1R2 (14% identical), LAG3 (10% identical), SIGIRR (9% identical).
Diseases named in the same sentence as IL1RAPL1 in open-access papers:
IL1RAPL1 is named in the same sentence as 44 diseases in open-access papers, as found by Europe PMC text mining. Sharing a sentence is not in itself a finding about the gene and the disease. The quoted sentences say what the papers report.
Intellectual disability (15 papers, 2013 to 2025). "Exonic point mutations, deletions, and duplications of IL1RAPL1 have been associated with ASD and intellectual disability, suggesting that IL1RAPL1 is dosage-sensitive to both gain and loss of expression." (PMID 39019033, 2024). "For example, IL-1 receptor accessory protein like 1 (IL1RAPL1) mediates the activity of IL-1β and is involved in dendritic morphology, and genetic deletion of IL1RAPL1 causes intellectual disability and ASD." (PMID 33802132, 2021). "IL1RAPL1-deficient mice exhibit a decrease in dendritic spine density and deficits in learning, which is consistent with the association of IL1RAPL1 mutations and X-linked mental retardation and startle epilepsy." (PMID 34073798, 2021). "The gene IL1RAPL1 has been shown to be located in excitatory synapses, to play a role in synaptic differentiation, and be associated with cases of non-syndromic intellectual disability." (PMID 29685133, 2018). "Synaptic PTPRD interacts with IL1RAPL1 which defects have been associated with intellectual disability (ID) and autism spectrum disorder." (PMID 26082802, 2015). "Interleukin-1 receptor accessory protein-like 1 (IL1RAPL1) is associated with mental retardation (MR) and autism spectrum disorder (ASD)." (PMID 23785489, 2013). "IL1RAPL2 is closely related to IL1RAPL1, which has been associated with mental retardation, autism and psychiatric disorders, all of which are conditions associated with PTD." (PMID 23613933, 2013). "Mutation or loss of IL1RAPL1 results in intellectual disability and the unstable chromatin transition interval is almost always lost or rearranged in patients, suggesting that the two may be mechanistically linked." (PMID 30103804, 2018). "Finally a 1 year old boy who had global developmental delay carried a ~200 kb Xp21.3 deletion containing the IL1RAPL1 gene, which is linked to non-specific X-linked mental retardation." (PMID 27034718, 2016). "In contrast, IL1RAPL1 knockout, a genetic model of intellectual disability in which synaptic plasticity is also impaired did not alter NMDAR surface dynamics in hippocampal neurons." (PMID 34462417, 2021).
autism (8 papers, 2010 to 2023). Persistent deficits in social interaction and communication and interaction as well as a markedly restricted repertoire of activity and interest as well as repetitive patterns of behavior. "PTPRD, the human counterpart of Lar, interacts with IL1RAPL1, which is implicated in mental retardation and autism." (PMID 22715409, 2012). "Researchers in other studies have also suggested that IL1RAPL1, which is closely related to the IL1RAPL2 gene, identified in this study, is associated with autism." (PMID 22050706, 2011). "Mutations in IL1RAPL1 have recently been associated with autism spectrum disorders and a missense mutation (R102Q) on NCS-1 has been found in one individual with autism." (PMID 20479890, 2010). "Females carrying a loss of function mutation in IL1RAPL1 were found to exhibit a spectrum of phenotypes ranging from no obvious impairment to autism with or without mild mental retardation." (PMID 20479890, 2010).
autism spectrum disorder (8 papers, 2010 to 2022). A spectrum of developmental disorders that includes autism, and Asperger syndrome. "IL1RAPL1 is involved in regulating neuron development, and mutations in IL1RAPL1 have been reported to cause X-linked intellectual disability and autism spectrum disorder, and it is downregulated in brain tumor cell lines and xenografts." (PMID 30103804, 2018). "In a recent study, linkage analysis has suggested an association between loss of function mutations in the gene encoding IL1RAPL1 and a number of cases of familial autism and autistic spectrum disorder (ASD)." (PMID 20479890, 2010). "The disruption or deletion of the IL1RAPL1 gene is found to be associated with the BD trait in our association analysis whose disruption or deletion was previously detected in individuals with mental retardation and/or autism spectrum disorder." (PMID 35610583, 2022). "Furthermore, IL1RAPL1 genomic instability has been implicated in numerous other neurological and neuropsychiatric disorders including startle epilepsy, autism spectrum disorder and schizophrenia." (PMID 30103804, 2018). "In humans, IL1RAPL1 and PTCHD1 mutations are found in X-linked ID or X-linked autism spectrum disorders." (PMID 36551904, 2022). "Interleukin-1 receptor accessory protein-like 1 (IL1RAPL1) is associated with X-linked mental retardation and autism spectrum disorder." (PMID 23785489, 2013).
brain tumor (3 papers, 2012 to 2022). "Based on our data, we would predict that full-length IL1RAPL1 would be downregulated, which is indeed the case in brain tumors." (PMID 30103804, 2018). "IL1RAPL1 has been reported to be downregulated in many brain tumor cell lines and xenografts compared with normal tissues suggesting that it may function as a tumor suppressor." (PMID 22928040, 2012). "It was reported that IL1RAPL1 and DMD are two large genes located immediately adjacent to each other within the common fragile site region of instability, which are active in normal brain tissue but are under-expressed in every brain tumor cell line and xenograft." (PMID 35610583, 2022).
Duchenne muscular dystrophy (3 papers, 2022 to 2025). Duchenne muscular dystrophy (DMD) is a neuromuscular disease characterized by rapidly progressive muscle weakness and wasting due to degeneration of skeletal, smooth and cardiac muscle. "Among these SNPs, rs12557060 is within the gene interleukin-1 receptor accessory protein-like 1 (IL1RAPL1) and SNP rs331318 is located in the gene Duchenne muscular dystrophy (DMD)." (PMID 35610583, 2022).
breast carcinoma (2 papers, 2023 to 2024). "Interestingly, IL1RAPL1 expression correlates with improved prognosis in patients with mammary carcinoma and with the γδ T-cell marker ZBTB16." (PMID 39209451, 2024). "There have been a few studies that explored CSC-macrophage interactions such as PLGF-VEGFR1 and IL1RAPL1-IL-8 in glioma, AGER-S100A9 in hepatocellular carcinoma, CD90-CD11b in mouse breast cancer, and hCAP-18/LL-37-FPR2 and P2X7R in pancreatic ductal adenocarcinoma." (PMID 37249733, 2023).
X-linked intellectual disability (2 papers, 2013 to 2018). An X-linked intellectual deficiency in which not enough information is known, reported or published to indicate whether a gene causes non-syndromic or syndromic presentations. "For example, mutations in IL1RAPL1 have been observed in cases of X-linked intellectual disability, and the encoded protein has been shown to play a role in voltage-gated calcium channel regulation in cultured cells." (PMID 23341896, 2013).
Anxiety (1 paper, 2023). Intense feelings of nervousness, tension, or panic often arise in response to interpersonal stresses. "Finally, loss of Il1rapl1 in mice leads to behavioral changes opposite to those typically associated with ASD, including decreased anxiety and repetitive behavior." (PMID 37514044, 2023).
Arrhythmia (1 paper, 2023). Any cardiac rhythm other than the normal sinus rhythm. "PTPRQ, PLEKHB2, IL1RAPL1, and EXT1 are predicted to be involved in biological processes such as heart and large blood vessel development, as well as cardiac phenotypes such as arrhythmias, valve diseases, and cardiomyopathy." (PMID 37684230, 2023).
Autoimmunity (1 paper, 2019). The occurrence of an immune reaction against the organism's own cells or tissues. "Several genes, such as TREX1, FLI1, EVI5, IL1RAPL1, are known for their role in autoimmunity, with EVI5 being an established MS risk gene, whereas others, such as CBFB, OPCML and KMT2A, are involved in lymphoproliferative disorders (OMIM)." (PMID 30541027, 2019).
colitis (1 paper, 2022). Inflammation of the colon. "In conventionally housed IL-37tg mice with DSS induction, IL-37 receptors Il-18r1 and Il1rapl1 mRNA levels and additional downstream signaling pathway genes (Jun, Myd88, Sigirr, Smad3, Stat1, and Stat3) were expressed similarly as in control WT colitis mice." (PMID 35836813, 2022).
major depressive disorder (1 paper, 2021). An episode of depression lasting two or more weeks without an intervening episode of mania. "Further, there has been consistent support for a link between methylation of IL1RAPL1 and major depressive disorder (MDD), with identified probes showing higher methylation in MDD cases than controls." (PMID 30842574, 2021).
tumor (19 papers, 2012 to 2025). "Across 33 TCGA tumor types, the pan-cancer co-expression analysis identified three transcripts—IL1RAPL1, KCNK9, and TMEM169—that consistently tracked with OPCML." (PMID 41561740, 2025). "In-silico analysis showed that several genes (CASZ1, IL1RAPL1, SOX17, N4BP1 and ARHGDIA) suggested to have tumor suppressive functions were target genes of miR-151." (PMID 22928040, 2012).
head and neck tumors (1 paper, 2024). "In this study, it was found that IL-1α, IL-1β, IL1R1, IL1RL1, IL1F10, IL33, CASP1, and AIM2 were highly expressed in head and neck tumors, while IL1RN, IL1RAPL1, IL1RAPL2, IL18BP, IL18R1, and IL18RAP were low in expressed, which is consistent with previous literature." (PMID 39461030, 2024).
neurological disorders (1 paper, 2018). "The link between SETDB1 and neurological disorders extends beyond what is described here for IL1RAPL1, as neuronal ablation of SETDB1/Setdb1 results in heterochromatin loss and disrupted expression at the protocadherin cluster." (PMID 30103804, 2018).
IL1RAPL1 also shares sentences with these, for which no sentence is quoted: cancer (11 papers); liver cancer (4); schizophrenia (3); developmental delay (2); hematological malignancies (2); hepatocellular carcinoma (2); neurodevelopmental disorder (2); non-small cell lung carcinoma (2); bipolar disorder (1); cardiomyopathy (1); cognitive deficits (1); congenital adrenal hypoplasia (1); epilepsy (1); glioma (1); heart disease (1); hepatitis C (1); hypertriglyceridemia (1); lymphoproliferative disorders (1); melanoma (1); membranous nephropathy (1); memory impairment (1); metastatic cancer (1); microcephaly (1); Obesity (1); pancreatic ductal adenocarcinoma (1); psychiatric disorder (1); small cell lung carcinoma (1); trigonocephaly (1); X-linked AHC (1).